KLKB1 (kallikrein B1)
Diseases named in the same sentence as KLKB1 in open-access papers (continued):
Sharing a sentence is not in itself a finding about the gene and the disease.
coronary disease (1 paper, 2016). "After correcting for testing multiple SNPs by the Bonferroni correction method, only SNP rs3733402 (KLKB1 gene) was significantly associated with an outcome of having a history of angiographic coronary disease (adjusted P < 0.0125)." (PMID 27200353, 2016). "When subject age, male gender, and weight are taken into account, KLKB1 SNP rs3733402 significantly associates with those with a reduced history of angiographic coronary artery disease." (PMID 27200353, 2016). "Alternatively, having the G allele for rs3733402 (KLKB1 gene) decreased the odds of having a history of angiographic coronary disease by 24% [OR = 0.759; 95% CI = (0.622, 0.927)]; P = 0.007 that was statistically significant (P < 0.01) after Bonferroni correction for multiple hypothesis testing." (PMID 27200353, 2016). "Alternatively, having the rarer G allele compared to not having the G allele for rs3733402 (KLKB1 gene) decreased the odds of having a history of angiographic coronary disease by 24% [OR = 0.759; 95% CI = (0.622, 0.927); P = 0.007]." (PMID 27200353, 2016).
epilepsy (1 paper, 2014). A brain disorder characterized by episodes of abnormally increased neuronal discharge resulting in transient episodes of sensory or motor neurological dysfunction, or psychic dysfunction. "We therefore hypothesize that KLKB1-mediated reduction of scuPAR as identified in this study may play an important role in scuPAR-associated diseases, such as prostate and breast cancers, epilepsy, cardiovascular disease, and FSGS." (PMID 24249636, 2014).
hepatocellular carcinoma (1 paper, 2022). A malignant tumor that arises from hepatocytes. "For example, the biological function of KLKB1 is usually associated with coagulation surface-dependent activation, fibrinolysis, and inflammation, and high KLKB1 expression in patients with hepatocellular carcinoma predicts a good prognosis." (PMID 36059641, 2022).
liver disease (1 paper, 2024). "By training random forest models, a biomarker panel comprising KNG1, F11, KLKB1, CAPNS1, CDH1, CPN2, NME2, was identified by feature selection for liver disease detection." (PMID 39207047, 2024).
obstructive lung disease (1 paper, 2014). "Therefore, although KLKB1 regulation of scuPAR is a regulatory pathway observed in both disease and control populations, results from the activity assay and GWAS heterogeneity tests allow us to propose a significantly reduced KLKB1 activity in obstructive lung disease." (PMID 24249636, 2014).
prion disease (1 paper, 2014). A transmissible disease that is caused by a protein that is able to induce abnormal folding of normal cellular proteins, leading to characteristic spongiform brain changes, which are associated with neuronal loss without an inflammatory response. "Four proteins (NRXN2, KLKB1, KARS, and LAMA3) that harbour rarely observed single-nucleotide variants showed biological interactions that are associated with prion diseases and/or prion protein in our biological network analysis." (PMID 25149502, 2014). "Four proteins (NRXN2, KLKB1, KARS, and LAMA3) that harbour rarely observed SNVs have biological interactions that are associated with prion diseases and/or prion protein." (PMID 25149502, 2014).
sarcopenia (1 paper, 2026). Progressive decline in muscle mass due to aging which results in decreased functional capacity of muscles. "Compared to the stable nonsarcopenic group, individuals who developed sarcopenia demonstrated significant APOA1 (fold change -1.42, p < 0.001) and KLKB1 downregulation and LECT2 upregulation." (PMID 41782349, 2026).
tumor (5 papers, 2019 to 2022). "CLEC3B, KLKB1, and LRG1 displayed significant difference at RNA level among the tumor stages and patient survival time." (PMID 32545216, 2020). "Our results indicated that the expression of KLKB1 (P < 0.01), IL13RA2 (P < 0.01), ABCC8 (P < 0.01), and PART1 (P < 0.0001) was consistent with our bioinformatics analysis, which was significantly up-regulated in PanNETs compared with the non-tumor tissues." (PMID 31607839, 2019). "The results showed that the expression of KLKB1 (P < 0.01), IL13RA2 (P < 0.01), ABCC8 (P < 0.01), and PART1 (P < 0.0001) was significantly up-regulated, while PCSK2 (P < 0.01) was significantly down-regulated in PanNET tissues compared to the non-tumor tissues." (PMID 31607839, 2019). "Moreover, the expression levels of the CAT, ESR1, and KLKB1 genes were significantly correlated with the HCC stage (P < 0.05), while MMP9 was not significantly correlated with the tumor stage." (PMID 34671598, 2021).
cardiovascular disease (4 papers, 2014 to 2024). "A cross-sectional investigation determined if there is an association of PRCP and KLKB1 polymorphisms with cardiovascular disease (CVD)." (PMID 27200353, 2016). "Association of cardiovascular disease outcomes with SNPs in the PRCP and KLKB1 genes controlling for age, weight, and gender." (PMID 27200353, 2016).
cancer (3 papers, 2014 to 2022). A tumor composed of atypical neoplastic, often pleomorphic cells that invade other tissues. "KLKB1 is involved in protease inhibition and inflammatory cascades, and play a role in cancer progression, while the underlying mechanism needs further research." (PMID 31607839, 2019).
infection (3 papers, 2022 to 2025). The state of being infected such as from the introduction of a foreign agent such as serum, vaccine, antigenic substance or organism. "By day 5 after infection, bacterial load in Klkb1−/− mice was over 10-times higher than in WT animals (22.6 ± 9.0 × 107 versus 1.8 ± 0.8 × 107 photons/sec, P < 0.05 versus Klkb1−/−)." (PMID 40261297, 2025). "Bacterial bioluminescence signals at the infection site in Klkb1−/− mice were significantly elevated compared with WT animals (8.9 ± 2.0 × 107 versus 2.9 ± 1.0 × 107 photons/sec at day 2; P < 0.05 versus WT)." (PMID 40261297, 2025). "Infection with WNV induced expression of serum proteins associated with acute phase responses and inflammatory processes including complement pathway proteins C4B, and kallikrein (KLKB1), both of which are involved in complement activation." (PMID 36569838, 2022). "There was an increase in MAST4, FABP1, and KLKB1 levels that lasted until 18 h after LASV infection, whereas increased concentrations of IGFBP3 lasted until 48 h after infection." (PMID 35337059, 2022).
kidney disease (2 papers, 2016 to 2025). "Having established the platform-specific influence of APOL1, KLKB1, F12, and KNG1 variants on Olink and SomaLogic measurements of plasma APOL1, we investigated whether these variants may also be relevant to APOL1-associated pathologies, specifically kidney disease." (PMID 39975113, 2025).
KLKB1 also shares sentences with these, for which no sentence is quoted: myocardial infarction (2 papers); Sepsis (2); amoebiasis (1); angina (1); Arterial thrombosis (1); bone disorder (1); brain infarction (1); cognitive decline (1); Coma (1); diabetes (1); dilated cardiomyopathy (1); gastric cancer (1); heart disease (1); heart failure (1); hemorrhagic stroke (1); influenza (1); Liver Fibrosis (1); Nephropathy (1); nephrotic syndrome (1); neurological diseases (1); pancreatic neuroendocrine tumor (1); primary immunodeficiency (1); prostate carcinoma (1); skin infection (1); staphylococcus aureus infection (1); systemic lupus erythematosus (1); transthyretin amyloidosis (1); type 1 diabetes (1).